NR1H3 (nuclear receptor subfamily 1 group H member 3)
Description:
Nuclear receptor that exhibits a ligand-dependent transcriptional activation activity. Interaction with retinoic acid receptor (RXR) shifts RXR from its role as a silent DNA-binding partner to an active ligand-binding subunit in mediating retinoid responses through target genes defined by LXRES. LXRES are DR4-type response elements characterized by direct repeats of two similar hexanuclotide half-sites spaced by four nucleotides (By similarity). Interplays functionally with RORA for the regulation of genes involved in liver metabolism (By similarity). Induces LPCAT3-dependent phospholipid remodeling in endoplasmic reticulum (ER) membranes of hepatocytes, driving SREBF1 processing and lipogenesis (By similarity). Via LPCAT3, triggers the incorporation of arachidonate into phosphatidylcholines of ER membranes, increasing membrane dynamics and enabling triacylglycerols transfer to nascent very low-density lipoprotein (VLDL) particles. Via LPCAT3 also counteracts lipid-induced ER stress response and inflammation, likely by modulating SRC kinase membrane compartmentalization and limiting the synthesis of lipid inflammatory mediators (By similarity).
Synonyms: LXRA; LXR-a; RLD-1
Tractability: Small molecule: a drug acting on it is in phase 2 or 3 trials; a structure with a bound ligand is known; a high-quality ligand is known; it has a high-quality binding pocket; it belongs to a druggable protein family. PROTAC: UniProt records ubiquitination sites on it; ubiquitination databases record sites on it; a small molecule that binds it is known.
Target class: Nuclear hormone receptor subfamily 1 group H member 3; Nuclear receptor; Nuclear hormone receptor subfamily 1 group H; Nuclear hormone receptor subfamily 1; Transcription factor
Chemical probes: CHEMBL603956, GSK2033, GW-3965 (high quality), LXR-623 (high quality), PD080690, PD080875, PD080915, PD080985, PD081177, PD081420, PD081711, PD081987, PD082249, PD082460, PD082747, PD083021, PD083145, PD083755, PD083851, PD084123, and 8 more
Safety:
Unwanted effects reported when the protein is acted on. In parentheses: how it was acted on, where the effect was seen, and who reports it.
Increased, Liver Steatosis (activation; source: AOP-Wiki)
N/A, Liver Steatosis (activation; source: AOP-Wiki)
cardiovascular events (source: ClinPGx)
primary outcome (source: ClinPGx)
the primary outcome (source: ClinPGx)
Gene: Protein-coding gene on chromosome 11 (47,248,300 to 47,269,070, forward strand). Ensembl gene ENSG00000025434.
Subcellular location: Nucleus; Cytoplasm
Subcellular location (Human Protein Atlas): Nucleoplasm; Cytosol
Pathways (Reactome):
Signal Transduction: NR1H2 & NR1H3 regulate gene expression linked to gluconeogenesis; NR1H2 & NR1H3 regulate gene expression linked to lipogenesis; NR1H2 & NR1H3 regulate gene expression linked to triglyceride lipolysis in adipose; NR1H2 & NR1H3 regulate gene expression to control bile acid homeostasis; NR1H2 & NR1H3 regulate gene expression to limit cholesterol uptake; NR1H3 & NR1H2 regulate gene expression linked to cholesterol transport and efflux
Gene expression (Transcription): Nuclear Receptor transcription pathway
Metabolism: PPARA activates gene expression
Metabolism of proteins: SUMOylation of intracellular receptors
Transport of small molecules: VLDLR internalisation and degradation
Gene Ontology:
Molecular function: nuclear receptor activity; protein binding; sterol response element binding; transcription cis-regulatory region binding; cholesterol binding; DNA binding; DNA-binding transcription factor activity, RNA polymerase II-specific; RNA polymerase II cis-regulatory region sequence-specific DNA binding; chromatin DNA binding; DNA-binding transcription activator activity, RNA polymerase II-specific; DNA-binding transcription factor activity; sequence-specific DNA binding; zinc ion binding
Biological process: apoptotic cell clearance; cellular response to lipopolysaccharide; cholesterol homeostasis; hormone-mediated signaling pathway; mRNA transcription by RNA polymerase II; negative regulation of cholesterol storage; negative regulation of lipid transport; negative regulation of pinocytosis; positive regulation of cholesterol efflux; positive regulation of cholesterol transport; positive regulation of DNA-templated transcription; positive regulation of fatty acid biosynthetic process; positive regulation of lipid biosynthetic process; positive regulation of toll-like receptor 4 signaling pathway; positive regulation of transcription by RNA polymerase II; positive regulation of triglyceride biosynthetic process; response to progesterone; cell differentiation; intracellular receptor signaling pathway; lipid homeostasis; negative regulation of cold-induced thermogenesis; negative regulation of inflammatory response; negative regulation of macrophage activation; negative regulation of macrophage derived foam cell differentiation; negative regulation of pancreatic juice secretion; and 12 more
Cellular component: chromatin; nucleus; receptor complex; RNA polymerase II transcription regulator complex; cytoplasm; nucleoplasm
Genetic constraint (gnomAD): Loss-of-function variants: 18 observed, 47.98 expected, observed/expected ratio (o/e) 0.38, 90% interval 0.26 to 0.56. The upper end of that interval is the gene's LOEUF score, 0.56, which puts it in group 2 of 6, group 1 being the genes least tolerant of losing a copy. Missense variants: 486 observed, 619.08 expected, observed/expected ratio (o/e) 0.79, 90% interval 0.73 to 0.85. Synonymous variants: 232 observed, 237.29 expected, observed/expected ratio (o/e) 0.98, 90% interval 0.88 to 1.09.
Homologues: Orthologues: chimpanzee NR1H3 (98% identical), macaque NR1H3 (96% identical), rabbit NR1H3 (93% identical), mouse Nr1h3 (91% identical), pig NR1H3 (91% identical), guinea pig NR1H3 (91% identical), rat Nr1h3 (89% identical), dog NR1H3 (85% identical), zebrafish nr1h3 (66% identical), Drosophila melanogaster EcR (33% identical), Caenorhabditis elegans nhr-23 (21% identical), Caenorhabditis elegans sex-1 (21% identical), and 182 more. Paralogues in human: NR1H2 (63% identical), NR1H4 (33% identical), VDR (29% identical), NR1D2 (26% identical), NR1I2 (25% identical), NR1I3 (25% identical), RARG (25% identical), THRB (25% identical), NR1D1 (24% identical), RARA (24% identical), RARB (24% identical), RORC (24% identical), and 6 more.
Diseases named in the same sentence as NR1H3 in open-access papers:
NR1H3 is named in the same sentence as 85 diseases in open-access papers, as found by Europe PMC text mining. Sharing a sentence is not in itself a finding about the gene and the disease. The quoted sentences say what the papers report.
atherosclerosis (15 papers, 2005 to 2026). A disease characterized by the build-up of fatty material and calcium deposition in the arterial wall resulting in partial or complete occlusion of the arterial lumen. "Of these nine TFs that were associated with atherosclerosis, only Nr1h3 (encoding Liver X receptor alpha) was mechanistically associated with plasma lipids and atherosclerosis in GWAS." (PMID 37301941, 2023). "Second, NR1H3 regulates lipid homeostasis, inflammation and affects the process of arteriosclerosis, and moreover, atherosclerosis has a greater effect on the increase of SBP." (PMID 36950018, 2023). "Further studies are fruitful to determine how the interaction between Pten and Nr1h3 affects the pathogenesis of atherosclerosis beyond plasma atherogenic traits." (PMID 37301941, 2023). "Of the Nr1h3-dependent genes reported, ten genes showed strong correlations with Nr1h3 expression and atherosclerosis or plasma lipids in our DO-F1 cohort." (PMID 37301941, 2023). "The significantly expressed and atherosclerosis-associated genes (MSR1, CD36, NR1H3) were detected by transcriptome analysis." (PMID 36613720, 2022). "NR1H3 gene encodes liver X receptor alpha (LXRA), one of the key transcription factors for cholesterol efflux and inflammatory gene responses in macrophages, and thus takes part in the process of atherosclerosis." (PMID 36950018, 2023). "Lastly, we examined direct or indirect target genes of Nr1h3 to determine if the expression, genetic regulation, and correlation with aortic lesion area of Nr1h3 could affect the relationship between Nr1h3’s target genes and atherosclerosis." (PMID 37301941, 2023). "In rat atherosclerosis PCR array, Abca1, Bax, Bcl2, Bcl2a1, Cd44, Fabp3, Hbegf, Lypla1, Ptgs1, Selplg, Tgfb2, Tnc, and Vegfa had reverse trend between WT and MU groups, while the trends of Bcl2l1, Bid, Birc3, Cxcl1, Fas, Fn1, Itga2, Itga5, Lif, Nfkb1, Nr1h3, Ppard, and Sod1 were consistent." (PMID 34545275, 2021).
breast carcinoma (13 papers, 2016 to 2025). "To further explore the underlying mechanisms of NR1H3 in breast carcinogenesis, we investigated the correlation of NR1H3 expression with tumor-infiltrating immune cells of breast cancer." (PMID 36699456, 2022). "In order to reveal the relationship between gene mutation status and NR1H3 expression in breast cancer, we screened mutations resulting in NR1H3 expression change using muTarget tool." (PMID 36699456, 2022). "Here, we evaluated the association between NR1H3 expression level and breast cancer patients’ prognosis in multiple public databases." (PMID 36699456, 2022). "Importantly, the expression of NR1H3 and macrophage infiltration level were independent risk factors for prognosis of breast cancer patients." (PMID 36699456, 2022). "The results indicated that high expression levels of OPN4, NOS2, GPR157, NCOA2, CLOCK, and TH were associated with shorter OS in breast cancer patients, while high expression of EGR3, NR1H3, RELB, SIAH2, and ADRB1 was linked to improved survival rates." (PMID 41031266, 2025). "For grade 3 breast cancer patients, low expression of NR1H3 indicated a worse survival prognosis of OS (p = 0.01), RFS (p = 0.025) and DMFS (p = 0.035)." (PMID 36699456, 2022). "ROC Plotter showed that NR1H3 was upregulated in responders of luminal A (AUC = 0.564, p = 2.9e-02) and grade 1 subtype breast cancer patients with Tamoxifen treatment (AUC = 0.822, p = 1.1e-05) based on relapse-free survival (RFS) at 5 years." (PMID 36699456, 2022). "Immune-related gene NR1H3 is likely to be one of potential immune markers for breast cancer immunotherapy." (PMID 36699456, 2022). "Three breast datasets in the Oncomine were adopted for the validation of lower NR1H3 expression in breast cancer." (PMID 36699456, 2022). "In this study, we visualized the prognostic landscape of NR1H3 in breast cancer using databases, including TIMER2, GEPIA2, and Kaplan-Meier Plotter." (PMID 36699456, 2022). "Based on these results, we evaluated the prognostic efficiency of the combination of infiltrated macrophages and NR1H3 expression patterns for breast cancer." (PMID 36699456, 2022). "Here, we provide evidence that high expression of NR1H3 is strongly correlated with multiple immune infiltration in breast cancer tissues, including B Cells, CD4+ T Cells, CD8+ T Cells, neutrophils, macrophages and DCs." (PMID 36699456, 2022). "In the present study, we showed that NR1H3 was correlated with infiltrating level of macrophages as well as the expression of monocyte/macrophage markers in breast cancer." (PMID 36699456, 2022). "Here, we aimed to visualize the prognostic value and immunological characterization of NR1H3 in breast cancer." (PMID 36699456, 2022). "In breast cancer, NR1H3 was identified as an antiproliferative and adipogenic factor in breast cancer cells and proved that the antiproliferative effect of NR1H3 is independent of lipid biosynthesis." (PMID 35692496, 2022). "We observed that low expression of NR1H3 was found to be significantly associated with poor clinical outcome in basal subtype, HER2 positive subtype and grade 3 breast cancer patients." (PMID 36699456, 2022). "GO enrichment analysis revealed adaptive immune response and immune cells activation process were correlated with the expression of NR1H3 in breast cancer." (PMID 36699456, 2022). "To determine the expression pattern of NR1H3 in breast cancer, we analyzed the NR1H3 expression profile based on multiple public databases." (PMID 36699456, 2022). "As we expected, the low expression of NR1H3 and low M1 (anti-tumor)/high M2 (pro-tumor) macrophage infiltration predicted a poor prognosis in breast cancer patients." (PMID 36699456, 2022). "The current clinical data-based evidence supports the role of NR1H3 expression in the clinical features of breast cancer." (PMID 36699456, 2022). "In breast cancer, recent studies showed that NR1H3 is likely to be an onco-suppressor gene and related to immune infiltration." (PMID 36699456, 2022).
breast carcinoma (continued). "Then we evaluated the prognostic efficiency of the combination of infiltrated macrophages and NR1H3 expression patterns for breast cancer." (PMID 36699456, 2022). "NR1H3 was mainly expressed in immune cells, and its expression was closely related with infiltrating levels of tumor-infiltrating immune cells in breast cancer." (PMID 36699456, 2022). "Kaplan-Meier survival curves showed shorter overall survival in basal breast cancer patients with low NR1H3 expression, and poorer prognosis of relapse-free survival in breast cancer patients with low NR1H3 expression." (PMID 36699456, 2022). "Our results indicate that NR1H3 influences the prognosis of patients with breast cancer, probably via its interaction with infiltrating macrophages." (PMID 36699456, 2022). "Gene interaction network and functional enrichment analysis revealed the molecular mechanism by which low expression of NR1H3 gene leads to poor prognosis of breast cancer patients." (PMID 36699456, 2022). "In mouse models, NR1H3 ligands augments mammary-tumor growth and increases NR1H3-dependent metastasis." (PMID 36699456, 2022). "In the liver, NR1H2/NR1H3 stimulation results in sulfotransferase (an enzyme critical for estrogen deactivation) induction which inhibits breast-cancer growth in xenografted mice." (PMID 26894976, 2016). "On the basis of our analysis, we conclude that the Lipid-Sensors, NR1C3, NR1H2 and NR1H3 are likely to be onco-suppressors in breast-cancer." (PMID 26894976, 2016). "As for the potential role of NR1H2 and NR1H3 in breast-cancer, little and contrasting evidence is available." (PMID 26894976, 2016). "Importantly, the correlation analysis based on human breast cancer transcriptomic data (BRCA, TCGA cohort) shows a significant positive association between hypoxia activity scores and NR1H3 (LXRα) gene expression (R = 0.48, p < 2.2 × 10−16)." (PMID 40874205, 2025). "Moreover, the detailed mechanisms of NR1H3 in regulating activation of TME in breast cancer needs further study." (PMID 36699456, 2022). "Whether pharmacological NR1H3 agonists have potential preventive or therapeutic antitumor activity in breast cancer needs more studies to confirm." (PMID 36699456, 2022). "Moreover, NR1H3 expression and macrophage infiltration level were indicated as novel prognostic indicators for breast cancer, conferring significantly worse survival for those with low NR1H3 expression accompanied by a high level of infiltrated macrophages." (PMID 36699456, 2022). "ER-positive subtype had shorter RFS (p = 0.023) in breast cancer with low NR1H3 expression." (PMID 36699456, 2022). "Additionally, univariate and multivariate analysis indicated that the expression of NR1H3 and the level of macrophage infiltration were independent prognostic factors for breast cancer." (PMID 36699456, 2022). "Immunohistochemistry analysis using the tissue microarray (including 83 paired breast cancer and adjacent normal breast tissues) showed that the protein level of NR1H3 was significantly downregulated in breast cancer compared to adjacent normal tissues (p < 0.0001)." (PMID 36699456, 2022). "In conclusion, NR1H2/NR1H3 activation may represent a strategy for the treatment/chemoprevention of breast-cancer, although caution should be exercised, since NR1H2/NR1H3-agonists may favor the metastatic spread of tumor cells." (PMID 26894976, 2016). "However, the prognostic value and immunological characterization of immune-related gene NR1H3 in breast cancer remain unclear." (PMID 36699456, 2022). "Therefore, NR1H3 could be a useful biomarker in breast cancer patients and activation of NR1H3 might be a potential therapeutic antitumor strategy of breast cancer." (PMID 36699456, 2022). "Further analysis revealed that breast cancer patients with higher expression levels of cholesterol efflux-related genes, such as ApoA1 and NR1H3 (also known as LXRa), appeared to have extended survival rates." (PMID 38566092, 2024).